HSD17B1 (hydroxysteroid 17-beta dehydrogenase 1)
Diseases named in the same sentence as HSD17B1 in open-access papers (continued):
Sharing a sentence is not in itself a finding about the gene and the disease.
polycystic ovary syndrome (2 papers, 2022 to 2025). A disorder that manifests as multiple cysts on the ovaries. "Expression of genes related to steroid biosynthesis, mitochondrial metabolism, and known markers of polycystic ovary syndrome was found to be upregulated in adult HSD17B1-KI ovaries." (PMID 41219171, 2025). "Patients with polycystic ovary syndrome may have follicle development impairment due to elevated levels of estrogen and pregnenolone in follicular fluid; the mechanism is in part mediated by changes in the expression of HSD17B1, CYP19A1, and CYP11A1 in FF exosomes." (PMID 36210808, 2022).
adenomyosis (1 paper, 2022). The growth of endometrial tissue inside the muscular wall of the uterine corpus. "Therefore, the overexpression of HSD17B1 induces adenomyosis, which is involved in the biosynthesis of estrogens, again highlighting the important role of hyperestrogenism in the development of adenomyosis." (PMID 35330066, 2022).
bladder tumors (1 paper, 2024). "Investigating the specific mRNA expressions of HSD17B1 in bladder tumors showed a significant increase in the mRNA expression of HSD17B1 in BLCA tissues compared to the normal sample (p = 1.85E-05)." (PMID 38850011, 2024).
cervical cancer (1 paper, 2025). A primary or metastatic malignant neoplasm involving the cervix. "Moreover, the overexpression of the 17β-hydroxysteroid dehydrogenase type 1 (HSD17B1) in HeLa, SiHa, and CaSki, indicates the ability of HPV-positive cervical cancer cells to convert estrone to oestrogen locally." (PMID 40446016, 2025).
chronic obstructive pulmonary disease (1 paper, 2023). A chronic and progressive lung disorder characterized by the loss of elasticity of the bronchial tree and the air sacs, destruction of the air sacs wall, thickening of the bronchial wall, and mucous accumulation in the bronchial tree. "In addition, high expression of HSD17B1 is associated with deviated follicular fluid steroid levels in polycystic ovarian syndrome, foetal growth restriction, chronic obstructive pulmonary disease (COPD;; and other disorders including lung cancer, skin and eye diseases." (PMID 37188267, 2023).
colon cancer (1 paper, 2011). "We also found that 5-dAzaC, an inhibitor of DNMTs, induced the demethylation of the 5' flanking region of HSD17B1, leading to increased transcript and protein levels in HT29 colon cancer cells, which contributed to the increase in E2 formation." (PMID 22176788, 2011).
Down syndrome (1 paper, 2012). "In women with Down syndrome, we examined the relation of polymorphisms in hydroxysteroid-17beta-dehydrogenase (HSD17B1) to age at onset and risk of AD." (PMID 22474448, 2012).
endometrial disorder (1 paper, 2022). A non-neoplastic or neoplastic disorder that affects the endometrium. "HSD17B1 is considered as a promising drug target to inhibit estrogen-dependent growth of endometrial disorders." (PMID 35563206, 2022).
hyperandrogenism (1 paper, 2025). Excessive secretion of androgens from the adrenal glands or gonads. "Thus, the ovarian phenotype in the HSD17B mutant mice provides further evidence that reduced ovarian HSD17B1 activity may predispose to PCOS, and the HSD17B1KI mice present a novel animal model to identify the mechanisms behind the hyperandrogenism of PCOS." (PMID 41219171, 2025).
Klinefelter syndrome (1 paper, 2022). A sex chromosome disorder caused by the presence of an extra X chromosome in the male karyotype. "Similarly, overexpression of HSD17B1 and StAR protein was observed in testes of men with Klinefelter syndrome, suggesting overactivation of the hormones’ biosynthetic pathway in Leydig cells." (PMID 35336747, 2022).
myopia (1 paper, 2011). "We observed associations between certain combinations of polymorphisms at steroidogenesis enzyme genes (rs6203 [HSD3B1], rs10046 [CYP19A1], and sex) and high-myopia risk; meanwhile, there is evidence of correlations between rs605059 (HSD17B1)–sex interaction and sex hormone levels." (PMID 21921981, 2011).
Obesity (1 paper, 2015). Accumulation of substantial excess body fat. "Nevertheless, using a keyword search, we found a new promising study suggesting that weight loss in HSD17B1-deficient obese postmenopausal women by means of the appropriate diet and/or exercise reduces the risk of obesity-related cancers." (PMID 26694100, 2015).
ovarian carcinoma (1 paper, 2020). A malignant neoplasm originating from the surface ovarian epithelium. "HSD17B1 is overexpressed in E2-dependent cancers, such as breast, endometrial, and ovarian cancers." (PMID 33520998, 2020).
Ovarian cyst (1 paper, 2025). The presence of one or more cysts of the ovary. "In line with our data in mice, lowered expression of HSD17B1 has been reported in the blood of PCOS patients, and a case report associated a homozygous splice variant with poor ovarian response and ovarian cysts." (PMID 41219171, 2025).
urothelial carcinoma (1 paper, 2024). A malignant neoplasm derived from the transitional epithelium of the urinary tract (urinary bladder, ureter, urethra, or renal pelvis). "Our findings indicated that the expression of the HSD17B1 protein was moderate in normal BLCA, whereas it was medium to low in high-grade urothelial carcinoma patients' tissues." (PMID 38850011, 2024).
viral infection (1 paper, 2022). "Interestingly, the mRNA level of Hsd17b1 gene (a non-rate-limiting metabolic enzyme for both testosterone and estradiol biosynthesis) was markedly down-regulated following viral infection, which might account for the unchanged serum levels of testosterone and estradiol in SeV-infected mice." (PMID 35468896, 2022).
cancer (18 papers, 2010 to 2025). A tumor composed of atypical neoplastic, often pleomorphic cells that invade other tissues. "A series of bioinformatics techniques were applied to investigate the expression of HSD17B1 in different types of cancer and its potential association with the prognosis of BLCA patients using diverse databases." (PMID 38850011, 2024). "Other mRNAs such as BARX1, EIF3D, PPP1R7, and HSD17B1 are also known to be associated with different cancers or other diseases." (PMID 29270229, 2017). "These epigenetic differences were associated with a significant reduction of HSD17B1 transcript and protein levels in cancer located in the proximal colon." (PMID 22176788, 2011). "Additionally, we examined the correlation between the mRNA levels of HSD17B1 and individual cancer stages and detected a significant association between the HSD17B1 mRNA expression levels." (PMID 38850011, 2024). "A recent meta-analysis on the impact of HSD17B1 polymorphism rs605059 shows that it might confer genetic cancer susceptibility in Caucasians, but authors propose more studies are needed." (PMID 28430630, 2017). "In the present study, we hypothesized that HSD17B1 may be linked to carcinogenesis and cancer progression, and this gene may play vital roles in BLCA by activating or inhibiting metabolism-related pathways, hence influencing the chemicals and energy required for tumor cell growth and reproduction." (PMID 38850011, 2024). "Using the UALCAN, the mRNA expression of HSD17B1 was determined to investigate its expression in different cancer types." (PMID 38850011, 2024). "We found that the mRNA and protein levels of HSD17B1 were markedly higher in cancer samples than normal samples in patients, with a statistically significant association of p = 1.85E-05." (PMID 38850011, 2024). "Our findings suggested that mRNA and protein expression of HSD17B1 were significantly higher in cancer than in normal samples." (PMID 38850011, 2024). "Weak staining for HSD17B1 was seen in 38 control and 36 cancer samples out of 42 pairs investigated." (PMID 28690541, 2017). "With Solvay antibodies against HSD17B1 moderate staining was seen in control and cancer tissue in epithelial and stromal cells, with cytoplasmic but also some positive nuclear staining, and intense staining in placenta tissue (data not shown)." (PMID 28690541, 2017). "The inhibitors of reductive HSD17B1 enzymes can block the conversion of E1 to E2, and have potential for application to hormone-sensitive cancer therapy." (PMID 28674494, 2017). "Our results are in line with a low HSD17B1 expression levels observed in cancer and adjacent control tissue." (PMID 28690541, 2017). "Finally, qRT-PCR analysis revealed a significant upregulation of HSD17B1 mRNA expression level in the cancer cells compared to the human 293T cells, which was consistent with the bioinformatics data." (PMID 38850011, 2024). "Similarly, according to the TCGA-UALCAN data, we also showed that HSD17B1 expression level in cancer cells were more upregulated than the normal cells." (PMID 38850011, 2024). "A prior study indicated a connection between the HSD17B1 expression and DNA methylation in cancer." (PMID 38850011, 2024). "COMT and HSD17B1 were identified to be responsible for the differential estrogen response between ES clusters A and B, and the estrogen response may be correlated with the differentiation and cancer stemness of CCA at the single-cell level." (PMID 35664769, 2022). "Additionally, both HSD17B1 and HSD17B2 gene isoforms were found to be amplified minimally (0–1.4%) in different hormone sensitive cancers studied." (PMID 31060224, 2019). "However, a significant association has been observed in the mRNA expression level of HSD17B1 among cancer patients at stages 2, 3, and 4 compared to normal patients." (PMID 38850011, 2024).
tumor (12 papers, 2007 to 2025). "In non-small cell lung cancer (NSCLC), expression of HSD17B1 mRNA and proteins is markedly increased, causing tumor cell proliferation through enhanced E2 production." (PMID 36830409, 2023). "Expression analysis showed that HSD17B1 was predominantly localized in epithelial cells, consistent with the scRNA-seq results, and its generally elevated expression suggested a potential association with tumor progression." (PMID 41226409, 2025). "This study provides substantial evidence for the anti-tumor activities of kaempferol in both ER subtypes of EC cells and a positive association between HSD17B1 expression and kaempferol’s sensitivity; however, there are several limitations to consider when interpreting the findings presented." (PMID 36932403, 2023). "Pseudotime analysis revealed a progressive upregulation of HSD17B1 expression specifically during the transition of epithelial cells from normal phenotypes to malignant tumor cells." (PMID 41226409, 2025). "At the single-cell level, HSD17B1 was predominantly expressed in malignant epithelial clusters, and ST revealed its localization in tumor-enriched regions, providing robust spatial and cellular context to its pathogenic role." (PMID 41226409, 2025). "According to the findings, HSD17B1 exhibited significantly higher mRNA expression in various tumor samples than that of normal and primary samples." (PMID 38850011, 2024). "Similar results were observed in the IHC of HSD17B1 in nude mouse tumor tissue after several weeks of kaempferol treatment." (PMID 36932403, 2023). "HSD17B1 was identified as a potential core target, with its specific expression pattern observed in epithelial cell subsets, highlighting its functional relevance in tumor progression." (PMID 41226409, 2025). "We finally verified HSD17B1 expression level in various tumor cells by qRT-PCR analysis." (PMID 38850011, 2024). "In addition to the ovary and placenta, human HSD17B1 is highly expressed in some tumors and involved in the E2-mediated tumor progression." (PMID 36830409, 2023). "Interestingly, expression of several estrogen synthesis genes (CYP17A, CYP19, HSD17B1, CYP21 and HSD3B1) was detected more frequently in tumor tissue than in normal tissue, with CYP19 (aromatase) and HSD3B1 only detected in tumors." (PMID 29290988, 2017). "We also did not observe differences in HSD17B1 transcript and protein levels between these tissues in the female patient group, different ages, G1/G3 histological grade, and different tumour stage (not shown)." (PMID 22176788, 2011).
adenocarcinoma (1 paper, 2011). A common cancer characterized by the presence of malignant glandular cells. "It significantly downregulates the HSD17B1 transcript and protein in adenocarcinoma cells by repression of HSD17B1 gene transcription." (PMID 21845090, 2011).
HSD17B1 also shares sentences with these, for which no sentence is quoted: Alzheimer disease (2 papers); amyotrophic lateral sclerosis (1); colonic adenocarcinoma (1); diabetes (1); embryonal carcinoma (1); gastric adenocarcinoma (1); gestational diabetes (1); Gynecomastia (1); Huntington disease (1); hyperestrogenism (1); Insulin resistance (1); leiomyoma (1); leukemia (1); Lipedema (1); Onset (1); pancreatic cancer (1); Parkinson disease (1); seminoma (1); yolk sac tumor (1).